KCNJ3 (potassium inwardly rectifying channel subfamily J member 3)
Description:
Inward rectifier potassium channels are characterized by a greater tendency to allow potassium to flow into the cell rather than out of it. Their voltage dependence is regulated by the concentration of extracellular potassium; as external potassium is raised, the voltage range of the channel opening shifts to more positive voltages. The inward rectification is mainly due to the blockage of outward current by internal magnesium. This potassium channel is controlled by G proteins. This receptor plays a crucial role in regulating the heartbeat (By similarity).
Synonyms: GIRK1; Kir3.1; KGA
Tractability: Small molecule: an approved drug acts on it; a high-quality ligand is known; it belongs to a druggable protein family. Antibody: its Gene Ontology location is reachable by antibodies, with high confidence; UniProt predicts a signal peptide or a membrane-spanning region; the Human Protein Atlas places it where antibodies can reach. PROTAC: a small molecule that binds it is known.
Target class: Inwardly rectifying potassium channel; Potassium channels; Voltage-gated ion channel; Ion channel
Gene: Protein-coding gene on chromosome 2 (154,697,855 to 154,858,354, forward strand). Ensembl gene ENSG00000162989.
Subcellular location: Membrane
Subcellular location (Human Protein Atlas): Mitochondria; Plasma membrane
Pathways (Reactome):
Neuronal System: Activation of G protein gated Potassium channels; Inhibition of voltage gated Ca2+ channels via Gbeta/gamma subunits
Gene Ontology:
Molecular function: G-protein activated inward rectifier potassium channel activity; inward rectifier potassium channel activity; protein binding; phosphatidylinositol-4,5-bisphosphate binding; voltage-gated potassium channel activity involved in atrial cardiac muscle cell action potential repolarization; voltage-gated potassium channel activity involved in ventricular cardiac muscle cell action potential repolarization; voltage-gated monoatomic ion channel activity involved in regulation of presynaptic membrane potential
Biological process: potassium ion import across plasma membrane; membrane repolarization during atrial cardiac muscle cell action potential; potassium ion transmembrane transport; potassium ion transport; regulation of heart rate by cardiac conduction; ventricular cardiac muscle cell membrane repolarization; membrane repolarization during ventricular cardiac muscle cell action potential; regulation of presynaptic membrane potential; response to electrical stimulus
Cellular component: voltage-gated potassium channel complex; plasma membrane; cell surface; external side of plasma membrane; inward rectifier potassium channel complex; membrane; parallel fiber to Purkinje cell synapse; presynaptic membrane; T-tubule
Genetic constraint (gnomAD): Loss-of-function variants: 4 observed, 41.01 expected, observed/expected ratio (o/e) 0.0975, 90% interval 0.047 to 0.22. The upper end of that interval is the gene's LOEUF score, 0.22, which puts it in group 1 of 6, group 1 being the genes least tolerant of losing a copy. Missense variants: 271 observed, 656.35 expected, observed/expected ratio (o/e) 0.41, 90% interval 0.37 to 0.46. Synonymous variants: 227 observed, 249.08 expected, observed/expected ratio (o/e) 0.91, 90% interval 0.82 to 1.02.
Homologues: Orthologues: chimpanzee KCNJ3 (100% identical), macaque KCNJ3 (100% identical), dog KCNJ3 (99% identical), rabbit KCNJ3 (99% identical), mouse Kcnj3 (99% identical), pig KCNJ3 (99% identical), rat Kcnj3 (99% identical), tropical clawed frog kcnj3 (90% identical), zebrafish kcnj3a (83% identical). Paralogues in human: KCNJ5 (45% identical), KCNJ6 (44% identical), KCNJ9 (43% identical), KCNJ2 (40% identical), KCNJ12 (38% identical), KCNJ18 (38% identical), KCNJ4 (37% identical), KCNJ14 (36% identical), KCNJ8 (33% identical), KCNJ11 (33% identical), KCNJ1 (31% identical), KCNJ16 (29% identical), and 3 more.